CD4 (CD4 molecule)
Diseases named in the same sentence as CD4 in open-access papers (continued):
Sharing a sentence is not in itself a finding about the gene and the disease.
tumor (continued). "This is consistent with our observations that eribulin enhances the activation of CD4+ T-cells in vivo when combined with either a tumor or STING agonist." (PMID 36497445, 2022). "CXCL12 neutralization abolished the 7HP349 treatment–related increase in frequencies of CD8+ and CD4+ Teffs and tumor myeloid cell infiltrates consisting of IMs, granulocytes, M1 macrophages, M2 macrophages, pDC, and cDC2." (PMID 35552271, 2022). "In the subgroup with high expression of INMT, a variety of immune cells and tumor microenvironment components increased, such as B cell, T cell CD4+, T cell CD8+, macrophage, myoid dendritic cell, endothelial cells, and cancer-associated fibroblasts." (PMID 35252179, 2022). "For instance, numerous studies have demonstrated that T cell help by CD4+ T cells is required for anti-tumor efficacy of cytotoxic T cells." (PMID 36303101, 2022). "In the case of CD44-positive IF group, we observed the deconvolution result for each IF group and found out some sites were mainly composed of tumour cells and some other sites were composed of endothelial, fibroblast, and CD4 + T cells." (PMID 35534484, 2022). "In fact, tumor-related CD4+ T cells spontaneously produce IL-2, a cytokine essential for the development and activation of Tregs." (PMID 36068484, 2022). "Long-lasting anti-tumor efficacy was found to be dependent on the CD4+ T helper type (Th) 1-dominant memory response after the therapy." (PMID 35203498, 2022). "Immunofluorescence double staining for CD4 and PU.1 revealed significantly more PU.1+ CD4+ T cells in the lamina propria of tumour patients, suggesting that IL-9 producing cells in CRC and CAC are Th9 cells." (PMID 35793807, 2022). "Although the CD4+FoxP3+ Treg subset of CD4+ cells are a significant portion, CD4+FoxP3− T helper subset of T lymphocytes also have significant pro-tumour activity." (PMID 35260891, 2022). "A review of the literature clearly shows that CD4+ cells are predominant among lymphocytes infiltrating the tumor." (PMID 36362598, 2022). "CD4+ Th1 cells can also contribute to tumor vascular normalization through the production of IFN-γ in TME." (PMID 36569915, 2022). "pDCs recruited to the tumor promote the maturation of infiltrating or resident cDC1s and activate CD4+ T and CD8+ T cell responses." (PMID 36230990, 2022). "More potent tumor infiltration by CD4+ and CD8+ T cells, on the contrary, is often related to better patient survival and a higher response rate to immunotherapy." (PMID 36277972, 2022). "CXCL9/10/11 are ligands for CXC-chemokine receptor 3 (CXCR3), which is highly expressed on cytotoxic CD8+ T cells and IFN-γ-producing CD4+ T helper 1 cells, both of which provoke tumor cell killing and enhance inflammation in the TME." (PMID 36531014, 2022). "In contrast, single-cell analysis of CD4+ T cells showed several tumour-specific states, including various states of Tregs, which also included clonally expanded cytotoxic CD4+ T cell." (PMID 36159866, 2022). "A preponderance of CD8+ T cells and CD4+ T cells at the tumor–liver interface was related to longer overall survival and the presence of tumor-infiltrating CD4+ or CD8+ T cells." (PMID 35847907, 2022). "It has been well demonstrated that cTreg cells can infiltrate the tumor site and, due to the immune regulatory signals received within the tumor, differentiate from CD4+Foxp3GFP- T cells to CD4+Foxp3GFP+ T cells and expand and accumulate at this location." (PMID 35860556, 2022). "Although no relevant preclinical studies have confirmed the effect of CAFs on the proximity of CD4+ Treg to tumor cells in locally advanced NSCLC, our study provided a new direction for targeting CAFs to improve the immunosuppressive microenvironment." (PMID 36685566, 2022). "The CKB expression was positively correlated with tumor purity (Cox = 0.196, p = 1.01e−02) and infiltration of some immune cells, including CD4+ T cells (Cox = 0.161, p = 3.54e−02), MDSC (Cox = 0.227, p = 2.86e−3)." (PMID 35664305, 2022).
tumor (continued). "CD4+ T cells can not only kill tumor cells directly in an IFN-γ-dependent manner but also maintain and promote the survival of CD8+ T cells through activation of CD8+ T cells, generation of memory CTLs response, and so on." (PMID 35677557, 2022). "This can arise as a consequence of different factors in the tumor microenvironment (TME), including immunosuppressive cells (CD4+ T regulatory cells, myeloid derived suppressor cells, fibroblasts, tumor cells), cytokines such as TGFβ and VEGF, and hypoxia." (PMID 36531040, 2022). "At present, there is further research on the exhaustion of CD4+ T cells, which is beneficial to stimulating stronger anti-tumor immunity." (PMID 36119037, 2022). "Subsequently, we mined the TIMER database to explore the correlation between the expression of EpCAM and tumor-infiltrating immune cells including B cell, CD4+ T cell, CD8+ T cell, macrophage, neutrophil, and dendritic cell." (PMID 35517503, 2022). "To detect the effect of CXCL1 on the tumor microenvironment, we examined CD4, CD8, and CD163 expression in tumor tissues of each group of mice." (PMID 36434686, 2022). "The vaccine acts by recruiting different types of cells in the tumor microenvironment, such as CD4+ and CD8+ lymphocytes, granulocytes, macrophages, and dendritic cells, which lead the tumor cells to apoptosis." (PMID 36135300, 2022). "The percentages of B native cell and CD4 memory resting T cells and M2 macrophages were clearly lower in the tumor group than in the normal group." (PMID 35774278, 2022). "In a mouse model of glioma, anti-GITR monoclonal antibody therapy combined with the radiotherapy increased the ratio of CD4+ T cells to Tregs, promoted tumor regression, and significantly improved mouse survival rate." (PMID 35371055, 2022). "Effective anti-tumor response requires the synergy of CD4+ T cells, tissue-resident memory T cells (TRM), and other immune cells." (PMID 35198442, 2022). "Another study in PyMT implied that CDDO-Me decreased IL-10 and VEGF levels while increased TNF expression, concomitantly suppressed TAM tumor infiltration, and CD4 Foxp3 regulatory T cells." (PMID 35784750, 2022). "Surprisingly, the transfer of RepTILs with a high frequency of CD4+ TILs and subsequent trametinib treatment induced modest, albeit persistent, control of smaller tumor implants." (PMID 35740548, 2022). "We found that TAMs indeed present tumor antigens to effector CD4 T cells and that such presentation is necessary for tumor rejection." (PMID 35903540, 2022). "Tregs also act as immunosuppressive within the tumor microenvironment, repressing the function of CD4+, CD8+, and NK cells." (PMID 35448032, 2022). "CD4+ T cells are upstream activators of adaptive immunity, and their direct activation and targeting of the tumor antigens can initiate a robust antitumor immune response in cold tumors, which include early epithelial cancer and precancerous lesions." (PMID 35657353, 2022). "In the TME, CAFs-secreted CCL2, CCL5, CCL17, IL-1, IL-6, IL-13, and IL-26 can also promote a Th2 and Th17 CD4+ polarization, at the expense of anti-tumor Th1 response." (PMID 36338519, 2022). "In summary, as an immune-activating preventive and therapeutic strategy, CpG/αOX40/cGAMP combined with a whole-cell vaccine has the unique ability to amplify tumor-specific CD4+ T cells, which improves anti-tumor sensitivity and long-term tumor recognition." (PMID 35748951, 2022). "Seminal preclinical studies by Allison’s group demonstrated that CD4 CTLs can directly kill tumour cells and eradicate established tumours in an MHC class II-dependent manner." (PMID 35572552, 2022). "T lymphocytes are representing the majority of the tumor-infiltrating lymphocytes (TILs): cytotoxic T lymphocytes (CTLs), CD4+ T helper cells, and Tregs (CD4+/FoxP3+)." (PMID 35205842, 2022). "In CRC tumors, TSDR demethylation has been associated with STAT5 and TET2, and the expression of both is upregulated in CRC tumor-infiltrating CD4+ T cells." (PMID 35874729, 2022).
tumor (continued). "In cancer patients, PD-1+CD39+ memory CD4 T cells were tumor-Ag-specific, activated, and proliferating, yet exhibiting features of functional exhaustion." (PMID 35954341, 2022). "Tumour-infiltrating T cells (CD4+T cells and CD8+T cells, etc.)were identified to play crucial roles in OVCA." (PMID 35911442, 2022). "Ectopic expression of STAT5A enables the expansion of tumor‐specific CD4+ T cells and triggers antitumor CD8+ T‐cell responses." (PMID 35244291, 2022). "TH17 cell in the group of the CD4+ subpopulation T cells, on the contrary, generate IL-17A, IL-17F, IL-21, and IL-22, which induce tumor proliferation by favoring tissue inflammation." (PMID 36552048, 2022). "In a recent study, the mass spectrometry-based characterization of the antigenic landscape revealed several OvCa-associated CD4+ and CD8+ T-cell epitopes from a panel of tumor-associated antigens." (PMID 35565389, 2022). "The level of tumor infiltrating CD4+ T cells was evaluated after completion of all combination treatments." (PMID 35710296, 2022). "On the contrary, after cryo-thermal therapy, the percentages of CD4-CTLs and Tregs were both increased compared with those in tumor-bearing controls." (PMID 36389684, 2022). "Depletion of T cells in vivo abrogated the delay in tumor progression observed following vaccination, suggesting that both CD4 and CD8 T cells contribute to antitumor immunity induced by neoantigen vaccination." (PMID 36569934, 2022). "On the other hand, Tregs (Foxp3+ CD25+ CD4+ T cells) have been shown to be recruited by tumor cells in TME to fight antitumor immunity." (PMID 35444656, 2022). "We found that rAd-mIL-28B significantly inhibited tumor growth and reduced the frequency of splenic CD4+Foxp3+ T cells." (PMID 35935577, 2022). "While, the frequency of CD4+IFN-γ+TNF-α− T cells was related to poor prognostic markers as it was higher in patients with larger tumor size and higher stage and showed direct correlation with the number of involved LNs." (PMID 36376825, 2022). "CAF-S1 subset also can enhance the expression of PD-1 and CTLA-4 at the surface of CD4+ CD25+ FOXP3+ T lymphocytes to participate in the formation of immunosuppressive environment within tumor mass." (PMID 36324128, 2022). "Consistently, we found that both CD4+ and CD8+ T cells were able to facilitate short-term BsAb-induced target tumor cell lysis, with CD4+ T cell-mediated target cell lysis only being slightly less robust than that for CD8+ T cells." (PMID 35990699, 2022). "Multiple cytotoxic CD4+ T cell clusters were clearly defined using canonical markers, suggesting that these cells kill autologous tumor cells." (PMID 35504878, 2022). "First, CD4 education of TAMs can occur in tumors originating in different tissues, and in both spontaneous and transplantable tumor models, suggesting that it is a widespread phenomenon." (PMID 35903540, 2022). "The growth of tumor in both CD4+ and CD8+ T cell depletion groups increased faster than treated group, leading to diminished immunotherapy efficiency as determined by survival analysis." (PMID 35013252, 2022). "This, in the case of the B16 tumor model, was accompanied by an increase in CD8+ TILs, concurrent with a loss of suppressive CD4+ Tregs TILs." (PMID 36323740, 2022). "Some studies have found that the immune score of tumor tissue and serum IL-6, IL-11, or CD4 + /CD8 + T cells can also reflect the immune-inflammatory state, but the method is costly, inconvenient, and difficult to apply in clinical practice." (PMID 35866083, 2022). "Specifically, we focus on the latest progress regarding the impact of CD4+ T cell modulation on immunotherapies and other cancer therapies and discuss the prospect for harnessing CD4+ T cells to control tumor progression and prevent recurrence in patients." (PMID 35008422, 2022). "IL-28B reduced the frequency of splenic CD4+Foxp3+ cells in H22 tumor-bearing mice and the percentage of Foxp3+ cells after adding IL-28B at 5, 50, or 400 ng/ml." (PMID 35935577, 2022).
tumor (continued). "A high P-CA score presented high immune infiltration of CD4+ T cells; these immune cells are instrumental for controlling immune function, including immune surveillance of tumor cells." (PMID 36229828, 2022). "were significantly and positively correlated with CD4+ T lymphocyte in tumor (r = 0.49, 0.44, and 0.51, respectively, all p’s<0.05)." (PMID 35433455, 2022). "Tumor-infiltrating regulatory CD4+ T cells showed highly immunosuppressive properties and exhausted cytotoxic CD8+ T cells were highly expressed with markers of exhaustion." (PMID 35601491, 2022). "In an MPM patient cohort undergoing tumor resection, the number of CD4 and CD8 TILs varied between tumors." (PMID 34987640, 2022). "Although a variety of immunosuppressive T cells have been identified and studied, such as CD4+ type 1 T regulatory (Tr1) cells, the vast majority in the tumor microenvironment are still Treg cells (CD4+ CD25+ Foxp3+)." (PMID 36547564, 2022). "CD8+ T cells are the main effector cells to kill tumor cells, while activated CD4+ T cells can significantly increase the cellular components of innate immunity, such as macrophages and NK cells, by increasing the secretion of IFN-γ." (PMID 36386145, 2022). "For melanoma, T-VEC was already demonstrated to increase the number of tumor infiltrating CD4- and CD8-lymphocytes as well as activated CD8-lympho-cytes in the circulation and to rise expression of PD-L1 and IFNγ in virus-injected tumors." (PMID 36387105, 2022). "CD4+ T cells are also required for the induction of humoral immune responses against tumor antigens." (PMID 36230402, 2022). "The in-vivo expression of PD-L1 on A20 WT tumor cells (red dots) present in the metastatic nodules of the liver is higher than on either host B cells, CD4 T cells, or CD8 T cells (black dots)." (PMID 35795681, 2022). "ALMB-0168 reduces bone cancer growth in murine models WT Cx43; this drug also increases levels of cytotoxic lymphocytes (CD3/CD8+) and helpers (CD3/CD4+), increases the survival rate, and reduces tumor metastasis." (PMID 36176756, 2022). "Among them, the proportions of several anti-tumor immune cells, such as activated CD4 T cells, activated CD8 T cells, activated dendritic cells, and T follicular helper cells were significantly higher in m6Acluster A than those in m6Acluster B/C." (PMID 35528542, 2022). "In a previous report, the immune-mediated microenvironment in PDAC was found to contain a high percentage of CD4(+) T-cells and low percentage of tumor-infiltrating CD8(+) effector cells." (PMID 35673567, 2022). "The cDCs type 1 are specialized in activating CD8+ and type 2 on CD4+ T cells, both of which play a role in the regulation of anti-tumor immunity." (PMID 36232398, 2022). "More recent studies, however, demonstrate the importance of CD4+ T cells in anti-tumor responses, with a number of clinical and experimental studies reporting cytotoxic CD4+ T cells recognizing tumor neoantigens and or self-antigens." (PMID 35681695, 2022). "PGE2 can induce tumor growth and suppress immune functions by promoting the development of cluster of differentiation CD4+ and CD25+ regulatory T cells (Tregs) in the TME25." (PMID 35058524, 2022). "Elevated CD73 is associated with a decrease in CD4+, CD8+, and CD21+ tumor-infiltrating lymphocytes and is associated with aggressive clinical behavior." (PMID 35360246, 2022). "The most obvious perturbation induced by increased tumor burden was the downregulation of Cd4 c1 and upregulation of Cd4 c2, suggesting that tumor burden stimulated the production of naive Cd4+ T cells that were released in peripheral blood." (PMID 36438484, 2022). "Our research identifies a FOXP3+ Treg population in tumor-infiltrating CD4+ lymphocytes that are largely CCR4+." (PMID 35222362, 2022).
tumor (continued). "On the other hand, oral supplementation of non-responder patients with A. muciniphila upon FMT restored the anti-PDCD1 efficacy via IL12 by increasing the recruitment and infiltration of CXCR3+, CCR9+, CD4+ T cells into the mouse tumor site." (PMID 35463305, 2022). "We found that tumor-infiltrating CD4+ and CD8+ T cells were functionally inhibited by immunosuppressive ligands expressed on various types of myeloid cells or neutrophils in the process of oral carcinogenesis." (PMID 35972800, 2022). "The tumor-suppressing immune cells mainly consist of effector T cells (including cytotoxic CD8+ T cells and effector CD4+ T cells), B cells, NK cells, DCs, and M1-tumor associated macrophages." (PMID 35759090, 2022). "While the number of intra-islet T-cells was relatively low compared to the number of T-cells in the stroma, there were similarly more CD4+/Foxp3− Th-cells in the tumor islet in the control samples (p = 0.043)." (PMID 35565427, 2022). "Together, these results confirmed that SLC17A9 was associated with tumor infiltration by immune cells in LIHC, especially B cells, CD4+ T cells, and macrophages." (PMID 35957868, 2022). "By stimulating NK cells, CD8+ T cells, and other innate immune cells, CD4+ T cells can inhibit tumor progression, and cytokines produced by CD4+ T cells upon contact with tumor cell surface antigens can stimulate the production and activation of CD8+ T cells." (PMID 36555243, 2022). "CD4+ Th cells are divided into different subpopulations, including Th1, Th2, Th17, Tfh, and Tregs, and each subpopulation displays a specific role in tumor immune responses, inhibiting or promoting tumor cell growth." (PMID 36439457, 2022). "In our study, compared to wild type mice, more CD8+ Tnaive and less CD8+ Teff presented in tumor of Tmem176b−/− mice, and the same change had also been observed in tumor-infiltrated CD4+ T cells." (PMID 35399535, 2022). "Our observations that B7x can drive Treg induction from conventional CD4+ T cells demonstrate that it has additional roles in the tumor microenvironment in parallel to its established role as an inhibitory ligand to effector T cells." (PMID 35523809, 2022). "We separated the treated tumors into two groups based on their CD4 IFNγ expression levels and compared their tumor weights." (PMID 35651802, 2022). "Immunization of C57BL/6 mice with mTrop2 VLPs resulted in a significant reduction in tumor growth and broad activation of CD4(+) and CD8(+) T cells." (PMID 35214685, 2022). "Both tumor-bearing CD4+ T cells and cryo-thermal CD4+ T cells promoted the expression of CD86 in DCs and macrophages, but only cryo-thermal CD4+ T cells significantly upregulated the expression of MHC II in macrophages." (PMID 35874660, 2022). "Higher values of this signature indicate that more activated memory CD4+ T cells, more M1 macrophages, fewer resting Natural killer cells (NK cells), and fewer M0 macrophages were detected in patient tumour tissue." (PMID 36012105, 2022). "It was found that LUAD tumor tissue was significantly infiltrated by B cells naive, macrophages M1, plasma cells, DCs resting, T cells CD4 memory activated, T cells follicular helper and Tregs." (PMID 35710585, 2022). "More precisely, iNKT cells from liver, including CD4+iNKT cells and CD4–iNKT cells were better able to reject tumor cells than their counterparts from the spleen or thymus." (PMID 35915069, 2022). "It is possible that TME imposes a bottle-neck for the incoming tumor-specific CD4+ T cells due to hostile metabolic environment where the ones that differentiate into pTregs survive and others face their demise." (PMID 36248808, 2022). "By inducing the production of CXCL9 and CXCL10, these chemokines promote the recruitment of CD8+ and CD4+ effector T cells and inhibit tumor growth." (PMID 35590394, 2022). "We measured the ratio of CD4+/CD8+ T cells in tumor-bearing mice to better understand their immune function." (PMID 35363110, 2022).